Y_RNA (Y RNA )
Gene: Miscellaneous RNA gene on chromosome 20 (5,964,538 to 5,964,650, forward strand). Ensembl gene ENSG00000207380.
Homologues: Orthologues: chimpanzee Y_RNA (100% identical), macaque Y_RNA (92% identical). Paralogues in human: RNY1 (86% identical), Y_RNA (86% identical), Y_RNA (85% identical), Y_RNA (84% identical), Y_RNA (83% identical), RNY1P11 (82% identical), Y_RNA (82% identical), Y_RNA (81% identical), RNY1P7 (81% identical), Y_RNA (80% identical), RNY1P8 (79% identical), Y_RNA (79% identical), and 95 more.